STAT3 (signal transducer and activator of transcription 3)
Diseases named in the same sentence as STAT3 in open-access papers (continued):
Sharing a sentence is not in itself a finding about the gene and the disease.
heart failure (82 papers, 2010 to 2026). Inability of the heart to pump blood at an adequate rate to meet tissue metabolic requirements. "Aberrant activation of the JAK2/STAT3 pathway is associated with myocardial fibrosis and heart failure." (PMID 40290189, 2025). "The inactivation of STAT3 by gp130 loss in pressure-overloaded hypertrophy model mice increased cardiac failure." (PMID 37234159, 2023). "Collectively, these results showed that HSP22 protects against heart failure in cardiac pressure overload by associating with STAT3 phosphorylation, leading to the expression of stress and inflammatory genes that appear to offer protection from heart failure." (PMID 35011676, 2021). "Constitutive cardiomyocyte-restricted deletion of Stat3 has been found to result in increased apoptosis and increased susceptibility to doxorubicin-induced heart failure." (PMID 29245928, 2017). "In contrast, persistent and excessive STAT3 activation has been linked to adverse outcomes, including increased inflammation, ventricular rupture, and heart failure." (PMID 28686615, 2017). "In another study, they demonstrated that animals with the cardiomyocyte-restricted STAT3 KO are more susceptible to doxorubicin-induced cardiac injury and develop heart failure." (PMID 22675647, 2012). "Signal transducer and activator of transcription 3 (STAT3) has been linked to a number of pathological processes in heart failure, including ECM accumulation, collagen generation, and inflammatory responses, all of which mediate MEG3 activation in various cardiovascular signal transduction pathways." (PMID 36968595, 2023). "Hence, we will further focus on the methylation levels of KRAS, IL10, TLR4 and STAT3, and further determine the risk of heart failure and patient stratification by the combination of methylation and transcriptional expression in the future." (PMID 36324504, 2022). "Moreover, cardiac-restricted deletion of STAT3 increases the susceptibility to doxorubicin-induced heart failure." (PMID 26536361, 2015). "In a previous experiment, we found that FZYX improves cardiac function and protects cardiomyocytes by regulating STAT3 expression and inhibiting apoptosis in a heart failure rat model." (PMID 40364827, 2025). "In a study on rats with heart failure, Stat3 was found to regulate monocyte chemotaxis, thereby contributing to the progression of heart failure." (PMID 38935597, 2024). "The first study demonstrated that OTUD1 promotes pathological cardiac remodeling and heart failure by targeting STAT3 in cardiomyocytes." (PMID 39309432, 2024). "The MI-induced heart failure rats showed increased expression of JAK/STAT3 signaling parameters in left ventricular tissue, which significantly exacerbated myocardial apoptosis." (PMID 39338297, 2024). "It is possible that the observed increases in the expression of SRC and STAT3 mRNA are a consequence of severe heart failure resulting from excessive exertion." (PMID 39654536, 2024). "Reports suggest that exercise can stimulate macrophages in heart failure mice to secrete IL‐10, promote p‐STAT3/S100A9 nuclear translocation, and regulate the differentiation of myeloid‐derived suppressor cells, thus achieving cardioprotection." (PMID 38504474, 2024). "STAT3 has been suggested to be an attractive therapeutic target for treating cardiac remodeling and heart failure." (PMID 36743695, 2023). "Rats with the cardiac-specific knockout of STAT3 also exhibited ventricular remodeling and heart failure." (PMID 36671504, 2023). "Stimulation of IL-13RA1/STAT3 signaling can induce the excessive accumulation of included extracellular matrix, cardiac fibrosis, chronic cardiac stress, and heart failure." (PMID 36978012, 2023). "It has been previously demonstrated that MYC, MAP2K1, and STAT3 all have a critical role in the development of heart failure." (PMID 37234159, 2023).
heart failure (continued). "The Cytokines of the IL-6 family can inhibit apoptosis and induce compensatory cellular hypertrophy via gp130 and STAT3, which in turn leads to dilated cardiomyopathy and heart failure." (PMID 36671504, 2023). "Cal, as a novel PI3K activator, reduces inflammation and fibrosis in heart failure through the AKT–IKK/STAT3 axis." (PMID 35264961, 2022). "Raloxifene attenuates cardiac remodeling and inflammation induced by pressure overload, and oxidative stress in heart failure by inhibiting IL-6/STAT3." (PMID 35812340, 2022). "Several studies reported that the deficiency of gp130 in pressure-overloaded hypertrophy model mice exacerbated heart failure through the inactivation of STAT3." (PMID 32178385, 2020). "Although either the overactivation or inhibition of STAT3 appears to exacerbate cardiac pathophysiology, the fibrotic and remodeling responses would vary among types of heart failure." (PMID 32178385, 2020). "The therapeutic roles of STAT3 in heart disease have been reported in previous studies using several models of heart failure, including gene-altered mice and cultured cardiomyocytes." (PMID 32178385, 2020). "Studies have also reported that captopril exerted a cardioprotective effect on heart failure by inhibiting phosphorylation of JAK2/STAT3." (PMID 31619994, 2019). "The N-terminus of AC6 is likely to anchor AC6 on the sarcolemmal membrane and activates the Src/STAT3 signaling to prevent death of myocytes induced by β-adrenergic stress in heart failure patients who usually have excessive sympathetic reflex." (PMID 28870220, 2017). "In contrast, Stat3 was previously shown to be a cardioprotective factor as deletion of this gene promoted inflammation, fibrosis and heart failure." (PMID 27764156, 2016). "Further studies should explore the role of STAT3 in protecting against calcium overload during heart failure." (PMID 26339633, 2015). "Second, mice with postnatal cardiac myocyte-targeted STAT3 KO encompassing exons for the DNA-binding domain develop heart failure with age." (PMID 26664907, 2015). "Because of the importance of STAT3/PHB1 complex in mitochondria as a therapeutic target in heart failure, the effects of flavaglines need to be examined in experimental models of this disease." (PMID 26536361, 2015). "Moreover, cardiac-specific deletion of the myocardial suppressor of cytokine signaling-3 (SOCS-3), the endogenous feedback inhibitor of STAT3, results in reduced myocardial remodelling and severity of heart failure in the 14-day post-infarcted mouse heart." (PMID 38256208, 2024). "Huo demonstrated that inhibiting the IL-6/STAT3 pathway could exert cardioprotective effects by mitigating oxidative stress-induced mitochondrial dysfunction in a heart failure model." (PMID 38319722, 2024). "The study also indicates that the three CSA-signature genes (MYC, MAP2K1, and STAT3) may not only act as potential biomarkers for heart failure but also be potential targets for future research in the development of new treatment strategies for heart failure." (PMID 37234159, 2023). "It is noteworthy that circulating levels of interleukin (IL)-6-related cytokines are predictors of mortality in human heart failure, while the expression and post-translational modifications of STAT3 are severely reduced in myocardial cells in patients with dilated cardiomyopathy." (PMID 37019881, 2023). "In a TAC mouse model, exogenous miRNA-148a inhibited the expression of glycoprotein 130 (GP130) which in turn suppressed the phosphorylation of STAT3 and the expression of cardiac remodeling related genes, leading to improved ventricular dilatation and heart failure." (PMID 36195937, 2022). "Recent evidence indicates that the sustained activation of STAT3 signaling after MI may contribute to adverse remodeling and progression to heart failure." (PMID 35264961, 2022). "Thus, for proper heart failure treatment, STAT3 activation should be fine-tuned at the physiological level." (PMID 32178385, 2020).
heart failure (continued). "Furthermore, through literature research, we found that some MYC target genes were previously reported involving the development of heart failure, including STAT3, PRMT1, PRKCH and HSPA4." (PMID 32460775, 2020). "It has been proposed that decreased expression of STAT3 in diseased hearts may contribute to the progression of heart failure, further suggesting that the dysregulation of the JAK/STAT pathway may contribute to the pathogenesis of RCM." (PMID 28098235, 2017). "Expression of Stat3 might depend on the duration of DM and the stage of diabetic cardiomyopathy or heart failure." (PMID 27496100, 2016). "Notably, STAT3 levels and activity in the heart are reported to be reduced with heart failure, aging, and diabetes." (PMID 26664907, 2015). "Here, we demonstrated activation of STAT3 in heart failure developed post MI." (PMID 25997003, 2015). "On the other hand, a recent study suggested that sustained activation of STAT3 signaling after MI may actually contribute to adverse remodeling and heart failure." (PMID 25997003, 2015). "The role of STAT3 in heart failure has been carefully studied by many researches." (PMID 23818963, 2013). "Thus, continuous STAT3 activation appears to be an important pathogenic factor in the susceptibility to myocarditis, favouring its progression to DCM and heart failure." (PMID 23460527, 2013). "Finally, we show that monomeric STAT3 levels are decreased in the Gαq model of heart failure in a redox-sensitive manner." (PMID 22905257, 2012). "Our study findings may have at least two major pathophysiological implications: First, STAT3 signaling in the heart may be modulated by redox status and attenuated by oxidative stress as in heart failure." (PMID 22905257, 2012). "We concluded that KN‐93 impaired angiogenesis and aggravated cardiac remodelling and heart failure via inhibiting NOX2/mtROS/p‐VEGFR2 and STAT3 pathways." (PMID 34845819, 2022). "Elsewhere, studies found that the activation of signal transducer and activator of transcription 3 (STAT3) is critical in β-adrenergic receptor-mediated pathological remodeling and heart failure." (PMID 33855020, 2021). "Taken together, these data suggest that STAT3, in addition to play a central role in EAM onset, is also crucial for its progression to heart failure and DCM." (PMID 23460527, 2013). "We previously reported that levels of monomeric STAT3 measured under non-reducing conditions were decreased in a redox-sensitive manner in the Gαq model of heart failure, although the pathophysiological relevance of this observation was not established." (PMID 30619368, 2018). "Since atrial natriuretic factor (ANF) is known as a marker for heart failure, we examined the mRNA expression level of ANF which was higher expressed in cardiac tissue of infected WT (7.20 ± 3.54 fold, P = 0.0823) and STAT3 KO (5.11 ± 1.18 fold, P = 0.0079) mice as in control animals." (PMID 22675647, 2012). "On the other hand, STAT3 activates the transcription regulator GATA4, thereby upregulating the expression of NPPA, MYH7, and MYH6, which interacted with each other to regulate the structure and function of the sarcomere, resulting in heart failure and arrhythmias." (PMID 36034815, 2022). "Moreover, we found that STAT3 in the heart is affected by oxidative stress in a disease state, as monomeric STAT3 levels were decreased under non-reducing conditions in the Gαq model of heart failure in a redox-sensitive manner." (PMID 26664907, 2015).
heart failure (continued). "Whether STAT3’s transcriptional activity is similarly affected in human heart failure is not known." (PMID 26664907, 2015).
squamous cell carcinoma (82 papers, 2006 to 2025). A carcinoma arising from squamous epithelial cells. "Another study reported that guggulsterone causes a decrease in the levels of phosphotyrosine STAT3 in multiple myeloma and squamous cell carcinoma." (PMID 36145523, 2022). "Furthermore, targeting STAT3 with dominant negative mutants of STAT3 or antisense oligonucleotides specific for the STAT3 DNA sequence causes reversion of the malignant phenotype of squamous cell carcinoma, suggesting that STAT3 is a key mediator for the pathogenesis of these cancers." (PMID 27367272, 2016). "Quercetin decreases the migration and invasion of squamous carcinoma cells by reducing the p‐Src and p‐Stat3." (PMID 41195524, 2025). "Treatment of a human squamous carcinoma cell line with quercetin and luteolin resulted in a decrease in protein levels of p‐STAT3 and a reduction in the migratory and invasive abilities of the cells." (PMID 41195524, 2025). "The induction of p‐Tyr STAT3 by inhibition of JNK with SP600125 has also been described in squamous carcinoma cells before." (PMID 40751475, 2025). "Protein tyrosine phosphatase-like A domain-containing 2 (HACD4/PTPLAD2) is a potential tumor suppressor in squamous carcinoma responsible for the inhibition of STAT3 phosphorylation." (PMID 39985075, 2025). "In squamous cell carcinoma cell lines, chemerin activates STAT-3 signaling, increasing production of IL-6 and TNF-α, leading to infiltration of neutrophils promoting tumor growth." (PMID 40299651, 2025). "Elevation of circRNA FAT1 (circFAT1) in squamous cell carcinoma (SCC) combines and controls the positive association between tumor stemness and immune evasion by stimulating the expression of STAT3 (signal transducer and activator of transcription 3)." (PMID 38329551, 2024). "There is a remarkable increase in STAT3 phosphorylation level at site Y705 in human squamous carcinoma tissues compared to their adjacent normal lung tissues, whereas the total STAT3 protein expression showed no distinguishable difference." (PMID 39099000, 2024). "Based on these studies, many experiments on the expression of PD-L1, T cells, and STAT3 in squamous cell carcinoma have been carried out." (PMID 37305382, 2023). "Recent studies have shown that periplogenin can target signal transducer and activator of transcription 3 (STAT3) to inhibit the growth of squamous cell carcinoma both in vivo and in vitro." (PMID 37081536, 2023). "In cultures of a squamous carcinoma cell line, E-cadherin and STAT3 colocalize and E-cadherin-based cell–cell contacts are necessary for STAT3 activity." (PMID 36120588, 2022). "Resveratrol blocks the STAT3 signaling pathway via induction of SOCS-1, thus attenuating STAT3 phosphorylation and proliferation in squamous cell carcinoma of the head and neck cells." (PMID 35566016, 2022). "STAT3 upregulates the expression of the ataxia telangiectasia-mutated and Rad3-related (ATR) in epidermoid carcinoma cells." (PMID 36313570, 2022). "In human epidermoid carcinoma cells, STAT3 overexpression promoted anti-apoptosis gene expressions, such as Mcl-1, Bcl-1, and STAT3 depletion, making cells susceptible to apoptosis." (PMID 36313570, 2022). "NF-κB acts as a key redox-sensitive transcription factor that can be stimulated by ROS, and ROS suppress STAT3 in human epidermoid carcinoma cell lines." (PMID 34645472, 2021). "Here, it is reported that elevated circular RNA FAT1 (circFAT1) in squamous cell carcinoma (SCC) unifies and regulates the positive association between cancer stemness and immune evasion by promoting STAT3 activation." (PMID 34258151, 2021). "In the case of skin cancers, particularly squamous cell carcinoma, higher levels of this miRNA seem to act as a protective factor by downregulating STAT3." (PMID 34439557, 2021).
squamous cell carcinoma (continued). "As a novel circular RNA implicated in cancer development, evaluation of circFAT1 in squamous cell carcinoma (SCC) unifies and regulates the positive association between cancer stemness and immune evasion by promoting STAT3 activation." (PMID 34587919, 2021). "It has been demonstrated that STAT3 inhibition sensitized for example squamous cell carcinoma to chemotherapy." (PMID 32046095, 2020). "Growing evidence has indicated that STAT3 signaling was involved in carcinogenesis, and immunotherapy response through regulating cancer cell differentiation and proliferation in human squamous cell carcinoma." (PMID 33005178, 2020). "To date, STAT3 has been found to be constitutively activated in a variety of human malignancies, including squamous cell carcinomas of the head and neck." (PMID 32382281, 2020). "In this study, we identified the function of Lu and Qu on inhibition Src/Stat3/S100A7 signaling in squamous carcinoma cells." (PMID 31731716, 2019). "STAT3 can be activated by diverse upstream kinases including cytokine receptors and tyrosine kinases, and STAT3 was activated in nearly 50 % of the squamous cell carcinoma." (PMID 26553224, 2015). "In human epidermoid carcinoma A431 cells, resveratrol was the only compound affecting the total level of the Stat3 protein, as it significantly diminished this transcription factor content in the nuclear fraction by 20 %." (PMID 25063218, 2014). "STAT3 has been shown to up regulate c-Fos expression in both hepatocellular and epidermoid carcinoma cells and results indicated this was a result of direct interaction of STAT3 with the c-Fos gene promoter." (PMID 24743777, 2014). "Since the signaling pathways mediated by STAT3, Notch1 and Wnt2 play beneficial roles in CC formation and progression, the effects of resveratrol on them in cervical adenocarcinoma (HeLa) and squamous cell carcinoma (SiHa) cells were analyzed." (PMID 25061499, 2014). "STAT3 decoy inhibited proliferation and STAT3 mediated gene expression in squamous cell carcinoma of the head and neck in vitro as well as in a xenograft model in vivo." (PMID 24199193, 2013). "Squamous cell carcinomas of the head and neck often rely on the activation of Stat3 for proliferation and survival." (PMID 21264347, 2011). "The STAT3 pathway is involved in the pathogenesis of EGFR-dependent squamous cell carcinoma (SCC)." (PMID 36145523, 2022). "Moreover, immunohistochemistry staining for phosphorylated STAT3 has also revealed the increased expression of activated STAT3 in human squamous cell cancer of the tongue correlated with poor prognosis in patients with HNC." (PMID 35401182, 2022). "Of note, the effect was more pronounced in the squamous cell carcinoma cell line, which may be due to more effective inhibition of STAT3 phosphorylation (left)." (PMID 33530306, 2021). "Also, cases of urothelial carcinoma showed highly significant elevated STAT3 percent and scores of expression compared to cases of cystitis and squamous cell carcinoma (p<0.01)." (PMID 32102537, 2020). "Furthermore, it has been suggested that IL-17A plays a critical role in promoting hyperproliferation in squamous cell carcinomas through the induction of STAT3 and its regulated oncogenic and antiapoptotic gene expression." (PMID 31083515, 2019). "Also, the STAT3/Akt/ERK signals contributed to endothelial cells-initiated cross-talk affected on squamous carcinoma cells." (PMID 29050226, 2017). "Thus the DAPK loss in tumor buds is well fitting with the observation that STAT3 is known to be upregulated at the invasion front of squamous cell carcinoma." (PMID 26405175, 2015). "In the current study, we investigated the effect of resveratrol and its two 4′-methylthio-trans-stilbene derivatives (3-M-4′-MTS; S2) (3,5-DM-4′′-MTS; S5) on EGFR and Stat3 activation in human immortalized HaCaT keratinocytes and epidermoid carcinoma A431 cells." (PMID 25063218, 2014).